FAP (fibroblast activation protein alpha)
Diseases named in the same sentence as FAP in open-access papers (continued):
Sharing a sentence is not in itself a finding about the gene and the disease.
colon carcinoma (continued). "They investigated BF211-03 in human colon cancer HCT-116 xenografts and found that BF211-03 has tumor selectivity properties, and after cleaving by FAP, it successfully turned to BF211." (PMID 37316886, 2023). "CAFs from breast, ovarian, lung, pancreas, and colon cancer have shown expression of PD-L1 and/or PD-L2; particularly the CAF-S1 FAP+ subset." (PMID 35745648, 2022). "The results obtained from the data available for colon cancer in Oncomine showed that the expression of TRPC3 was positively related with the expression of CAF marker genes (α-SMA and FAP)." (PMID 35870973, 2022). "Despite promising results in preclinical models, clinical studies evaluating the FAP inhibitory antibody sibrotuzumab (BIBH 1, Boehringer Ingelheim, Germany, a humanized version of a murine anti-human FAP mAb) were disappointing in colon cancer." (PMID 32899119, 2020). "Not only the level of FAP α, but also the location of FAP α, is related to poor prognosis of colon cancer patients." (PMID 26985769, 2016). "A significantly larger proportion of patients with scorable FAP-absent cancer tissues had primary tumors in the colon, with 50.0% of patients having left-sided colon tumors and 42.9% of patients having right-sided colon tumors." (PMID 39335130, 2024). "Regarding FAP, although the first few drugs on the list were not well studied, kinetin riboside was found to inhibit colon cancer cells or even stimulated apoptosis." (PMID 35910202, 2022). "In addition, the Oncomine and GEPIA databases showed that TRPC3 expression is higher in colon cancer tissues compared with normal colon tissues, and was positively correlated with the expression of the CAF genes alpha-smooth muscle (α-SMA/ACTA2) and fibroblast activation protein Alpha." (PMID 35870973, 2022). "In IHC analysis, ACTA2, but not FAP, was strongly detected in smooth muscle cells of colon cancer tumor tissues, indicating the lack of cell specificity in ACTA2 to define CAFs populations in colon cancer." (PMID 37964075, 2023).
sarcoma (55 papers, 2009 to 2026). A usually aggressive malignant neoplasm of the soft tissue or bone. "Fibroblast activation protein (FAP) is a type II serine protease that is overexpressed on cancer-associated fibroblasts and mesenchymal tumor cells in the stroma of sarcomas." (PMID 41226078, 2025). "While high levels of FAP are primarily found on cancer-associated fibroblasts (CAFs), some cancer cells such as sarcomas can also express substantial amounts of FAP." (PMID 39008063, 2024). "Fibroblast Activation Protein (FAP) is an emerging theranostic target that is highly expressed on cancer-associated fibroblasts and on certain tumor cells including sarcoma." (PMID 39008063, 2024). "The aim of this study was to characterize FAP expression in sarcomas to explore its potential utility as a diagnostic and therapeutic target and prognostic biomarker in sarcomas." (PMID 37333052, 2023). "Further investigation of FAP as a potential diagnostic and therapeutic target in sarcomas is warranted." (PMID 37333052, 2023). "In addition, a close correlation between the intensity of FAPI tumor uptake and PET and histopathological FAP expression was shown in sarcoma patients, underlining the notion that FAP expression of tumors can be reliably displayed in vivo with FAPI-PET." (PMID 37584717, 2024). "FAP is a membrane serine protease physiologically expressed in the granulation tissue of healing wounds, but is also expressed in both cancer-associated fibroblasts and sarcoma cells." (PMID 36765578, 2023). "Additionally, RNA sequencing data in publicly available databases were utilized to compare FAP expression in samples (n = 10,626) from various cancer types and evaluate the association between FAP expression and overall survival (OS) in sarcoma (n = 168)." (PMID 37333052, 2023). "FAP may serve as a potential diagnostic and therapeutic target in certain sarcomas subtypes." (PMID 37333052, 2023). "In this context, a recent study demonstrated high FAP expression in various sarcomas, underscoring the need for cautious interpretation of FAPI-PET/CT results and thorough differential diagnosis." (PMID 40694103, 2026). "FAP expression in different renal tumors, including RCC, was lower when compared with cancers with known FAP expression, such as sarcoma." (PMID 41101974, 2026). "Lastly, tumors of mesenchymal origin express FAP on both CAFs and tumor cells, which is of particular interest in sarcomas." (PMID 39572227, 2025). "For example, 68Ga-FAP-2286 was employed as an imaging agent in various solid tumors, breast, bladder, prostate, colorectal, head and neck, pancreatic, sarcoma, cholangiocarcinoma, and lung cancers." (PMID 41441395, 2025). "This approach identified a pool of sarcoma-specific genes, including many like FAP or MMP14 in UPS which are upregulated in STS compared to almost all normal cell types." (PMID 40814001, 2025). "Fibroblast activation protein (FAP) is a serine protease upregulated in abnormally activated stromal fibroblasts in many epithelial cancers and sarcomas." (PMID 40126602, 2025). "Currently in Phase 1/2 trials, 177Lu-FAP-2286 shows particular promise for advanced metastatic sarcomas and other FAP-rich malignancies." (PMID 40725089, 2025). "An association between tumoral [68Ga]Ga-FAPI uptake by positron emission tomography (PET) and histopathologic FAP expression has been observed in sarcoma patients." (PMID 39008063, 2024). "They mentioned that the main problem is the heterogeneity of the FAP expressed in the stromal cells and that only a few tumors, such as sarcomas and mesotheliomas, have FAP-positive tumor cells." (PMID 39770483, 2024). "In the tumor microenvironment of most epithelial malignancies and several mesenchymal origin malignancies, particularly sarcoma and mesothelioma, CAFs exhibit an uncertain presence of FAP on their cell surface." (PMID 38706713, 2023). "In the current study, the majority of sarcoma samples showed FAP expression by both stromal and tumor cells." (PMID 37333052, 2023).
sarcoma (continued). "Given the high expression of FAP in both stromal and tumor cells in various sarcoma subtypes, further studies to therapeutically target FAP in sarcomas are warranted." (PMID 37333052, 2023). "The current study provides insights into the immunomodulatory functions of FAP-targeted radiotherapy and demonstrates the therapeutic potential of combining 177Lu-FAP-2287 with an anti-PD-1 monoclonal antibody in a mouse sarcoma model." (PMID 37086273, 2023). "Herein, our first aim was to analyze the expression of FAP via immunohistochemistry (IHC) in tissue samples of patients with bone and soft tissue tumor subtypes, including sarcomas, available at our center." (PMID 37333052, 2023). "Advances in the management of sarcomas, including those subtypes with the highest FAP expression levels, is needed." (PMID 37333052, 2023). "In a mouse model of sarcoma, FAP-targeted radionuclide therapy induces an immunogenic TME through infiltration and activation of immune cells resulting in enhanced tumor efficacy when combined with PD-1 checkpoint inhibition." (PMID 37086273, 2023). "This includes understanding expression of FAP by CAFs and tumor cells in the sarcoma microenviroment." (PMID 37333052, 2023). "The majority of the existing literature is focused on FAP expression in epithelial cancers and there is limited data on FAP expression in sarcomas." (PMID 37333052, 2023). "Further work is needed including investigation of FAP expression in other sarcoma subtypes and further evaluation of expression in normal tissues." (PMID 37333052, 2023). "For imaging, we used the FAP-targeted inhibitor FAPI-46 for diagnostic work-up of cancer types such as pancreatic cancer and sarcoma." (PMID 34385340, 2022). "In comparison, in a large subset of sarcomas and mesotheliomas and smaller subset of epithelial derived cancers including esophageal, FAP expression was observed in tumor cells in addition to the CAFs population." (PMID 35608703, 2022). "Immunohistochemistry confirmed elevated levels of FAP expression in multiple tumor types including pancreatic, breast, and sarcoma, which correlated with FAP binding by FAP-2286 autoradiography." (PMID 35608703, 2022). "We found that FAP was overexpressed not only on CAFs of epithelial cancers, but also on mesenchymal cells of sarcomas." (PMID 36479116, 2022). "Recently, a study showed a strong association between tumor 68Ga-FAPi-46 PET uptake intensity and histopathologic FAP expression in sarcoma tumors." (PMID 34740953, 2022). "Since FAP is expressed in most epithelial cancers and sarcomas, it has a wide range of applications in cancer." (PMID 35186170, 2022). "Vice versa, co-stimulation through EpCAM or HER-2 significantly enhanced FAP-mediated tumor cell lysis, suggesting that T cells engaged carcinoma and sarcoma cells concomitantly." (PMID 34484225, 2021). "There is a correlation between tumoral FAPI uptake intensity and histopathological FAP expression in sarcoma patients, and FAPI PET has a high sensitivity." (PMID 34858834, 2021). "FAP is expressed in both the stroma and on neoplastic cells in sarcomas and thus appears important to sarcoma development." (PMID 34638433, 2021). "It is reasonable therefore that low-grade myofibroblastic sarcomas and fibroblastic areas of osteosarcoma abundantly expressed FAP and DPP-IV." (PMID 19817894, 2009). "In the TCGA sarcoma dataset, FAP varied by histotype but was clearly expressed in MPNSTs." (PMID 41591566, 2026). "Except for sarcoma, FAP is mainly expressed on CAFs in most solid tumors." (PMID 41425958, 2025). "Its radiolabeled form, 68Ga-FAP-2286, demonstrated sustained tumor uptake in a Phase I trial, supporting its role in baseline imaging and therapy monitoring across several solid tumors (e.g., breast, colorectal, sarcoma)." (PMID 41441395, 2025).
sarcoma (continued). "More importantly, FAP was found to be expressed in many different types of sarcoma tissue, including fibrosarcomas, malignant fibrous histiocytomas, leiomyosarcomas, osteosarcomas, chondrosarcomas, and liposarcomas, but not expressed in those with a “small round cell” phenotype." (PMID 40542914, 2025). "Peptide-based FAP-binding radiopharmaceuticals such as FAP-2286 demonstrate sustained retention for up to 10 days with short systemic exposure, translating into favorable clinical responses in both adenocarcinoma and sarcoma cohorts." (PMID 41463267, 2025). "A longer tumor growth delay was reported with [131I]I-GMIB-4AH29 in U87MG xenografts or with [177Lu]Lu-FAP2286 in a sarcoma PDX with high FAP expression on tumor cells, further highlighting how the targeted cell plays a crucial role in tracer accumulation, tumor MAD, and ultimately antitumor effect." (PMID 39266288, 2024). "FAP-targeting radioligands with longer tumor retention and radiotherapeutic strategies leading to higher tumor radiation doses may be required to enhance the efficacy of FAP-RLT in sarcoma." (PMID 39008063, 2024). "Both neoplastic and stromal cells show FAP expression in sarcomas." (PMID 37370912, 2023). "Thus, a more comprehensive understanding of FAP expression in sarcomas is critical to understand its potential utility as an imaging target for diagnosis, staging, treatment response evaluation, and as a potential therapeutic target." (PMID 37333052, 2023). "This indirect cytotoxicity of cancer cells may induce a direct immune response to cancer cells as has been shown in this study using a syngeneic model of FAP-expressing sarcoma." (PMID 37086273, 2023). "As sarcomas are derived from mesenchymal cells, FAP may also be used as a direct target for cancer cells in sarcomas." (PMID 37333052, 2023). "However, it should be noted that for some specific cancer type, FAP was highly expressed on both the tumor cells and stroma (e.g., sarcoma and mesothelioma)." (PMID 38706713, 2023). "Sarcomas were among cancer types with the highest mean FAP expression by RNA sequencing." (PMID 37333052, 2023). "Another potential immunogenic sarcoma antigen is fibroblast activation protein (FAP)." (PMID 36765578, 2023). "The efficacy of 177Lu-FAP-2286 was evaluated in the Sarc4809 PDX model of sarcoma." (PMID 35608703, 2022). "In addition, a comparison between the 2 techniques was performed using a set of cholangiocarcinoma and sarcoma whole tissue sections that were selected for varying FAP H-scores." (PMID 35608703, 2022). "In addition, in several tumors of mesenchymal origin, notably sarcoma and mesothelioma, FAP expression has also been observed on the neoplastic cells themselves and is similarly associated with promoting tumor progression and metastasis." (PMID 35608703, 2022). "In addition, there are many clinical trials underway for FAP-2286, which involve solid tumors such as breast, pancreas, sarcoma, prostate cancer (NCT04621435), and pathologic fibrosis such as idiopathic pulmonary fibrosis, cirrhosis, and cardiac fibrosis (NCT05180162)." (PMID 38543239, 2024). "In the HEK tumors that expressed FAP as well as xenografts derived from a sarcoma patient, [177Lu]Lu-FAP-2286 showed anti-cancer efficacy (e.g., 111% and 113% of tumor growth inhibition following 30 and 60 MBq [177Lu]Lu-FAP-2286, respectively) without causing any significant weight loss." (PMID 36813980, 2023). "However, the literature on FAP expression in sarcomas is limited." (PMID 37333052, 2023). "In sarcomas, many malignant cells themselves exhibit fibroblastic or myofibroblastic programs (e.g., α-SMA, FAP, PDGFRα/β, and vimentin)." (PMID 40940809, 2025). "In sarcomas, 68Ga-FAPI-46 PET demonstrated 96% sensitivity, with uptake correlating with FAP expression and altering staging or management in ~30% of patients." (PMID 41441395, 2025).
sarcoma (continued). "Until now, FAP-RLT has been tested preclinically in many immunocompromised xenograft models like human HT1080-FAP, HEK293-FAP and patient-derived sarcoma, as well as in human PANC-1 and MIA PaCa-2 xenografts." (PMID 39008063, 2024). "To address the limited efficacy of [225Ac]Ac-FAPI-46 observed in parental FSA tumors and to better recapitulate the high FAP expression in clinical sarcomas, we generated FSA cells overexpressing low, medium and high levels of murine FAP (FSA-F)." (PMID 39008063, 2024). "Another prospective study focused on [68Ga]Ga-FAPI-46 established a correlation between histopathological FAP expression and the intensity of [68Ga]Ga-FAPI-46 uptake in bone and soft tissue sarcomas in 47 patients with sarcomas." (PMID 39765634, 2024). "Results showed that FAP has a high accuracy (AUC ≥ 0.9) in predicting CESC, CHOL, COAD, ESCA, PCPG, sarcoma (SARC), and STAD." (PMID 37166418, 2023). "FAP is overexpressed in a wide range of tumors, some of which have a low avidity for 18F-FDG (i.e., sarcoma)." (PMID 35326586, 2022). "Additional research is required to realize the full potential of FAP expression and FAPI-PET/CT in sarcomas." (PMID 34638433, 2021). "A high expression of fibroblast activation protein (FAP) was observed in multiple sarcomas, indicating an enormous potential for PET/CT using 68Ga-radiolabeled inhibitors of FAP (FAPI)." (PMID 34018010, 2021). "Marker non-specificity (FAP, α-SMA, and PDGFRα/β) creates an on-target/off-tumor risk and, in sarcomas, can confuse stromal fibroblasts with malignant mesenchymal cells." (PMID 40940809, 2025). "Furthermore, Clovis Oncology has initiated a clinical evaluation of 68Ga-FAP-2286 (NCT04621435), which, as of June 2022, encompassed 48 patients with cancers of the breast, bladder, prostate, colon, head/neck, pancreas, sarcoma, cholangiocarcinoma, and lung." (PMID 38543239, 2024). "177Lu-FAP-2286 exhibited antitumor activity in FAP-expressing HEK293 tumors and sarcoma patient-derived xenografts, with no significant weight loss and longer tumor retention and suppression than treatment with radiolabeled FAPI-46 in animal studies." (PMID 37046676, 2023). "The majority of the sarcoma samples showed FAP expression by both stromal and tumor/nonstromal cells." (PMID 37333052, 2023). "177Lu-FAP-2286 exhibited antitumor activity in FAP-expressing HEK293 tumors and sarcoma patient-derived xenografts, with no significant weight loss." (PMID 35608703, 2022). "Moreover, FAP-2286 was further labeled with 177Lu and its biological behavior was examined in human FAP-transfected HEK 293 and patient-derived sarcoma Sarc4809 xenografts." (PMID 34681246, 2021). "Notably, the administration of 177Lu-FAP-2286 to HEK293-FAP tumor-bearing mice and FAP-expressing xenografts mice from sarcoma patients did not result in significant weight loss." (PMID 38543239, 2024). "Although sarcomas can have high uptake on FAP PET, it does not appear to improve staging compared to FDG PET, and its role may be limited to sarcomas with low FDG avidity and high FAP expression (e.g. solitary fibrous tumor) and selection for radioligand therapy (RLT)." (PMID 39572227, 2025).